MIR3125 (microRNA 3125)
Synonyms: hsa-mir-3125; mir-3125
Gene: MicroRNA gene on chromosome 2 (12,737,367 to 12,737,444, forward strand). Ensembl gene ENSG00000264370.
Diseases named in the same sentence as MIR3125 in open-access papers:
MIR3125 is named in the same sentence as 1 disease in open-access papers, as found by Europe PMC text mining. Sharing a sentence is not in itself a finding about the gene and the disease.
MIR3125 shares sentences with these, for which no sentence is quoted: cancer (1 paper).